INS (insulin)
Diseases named in the same sentence as INS in open-access papers (continued):
Sharing a sentence is not in itself a finding about the gene and the disease.
type 2 diabetes (continued). "Given the impairment in the normal pulsatility in insulin secretion observed in type 2 diabetes, it is conceivable that a derangement in the generation of cytosolic Ca2+ oscillations may even be a primary event which contributes to downstream production of ATP and hence insulin secretion." (PMID 23149488, 2013). "It has been demonstrated in several of the presented studies that insulin use during pregnancy is both a parameter of GDM severity and a strong predictor for the development of type 2 diabetes." (PMID 23819910, 2013). "After challenged by a high-fat diet, wild-type mice developed type 2 diabetes, but LTKO mice remained euglycemic and insulin-sensitive." (PMID 24015318, 2013). "Variant alleles at rs266729, which is associated with lower adiponectin levels, has been shown to be related with obesity, body mass index (BMI), type 2 diabetes (T2DM), diabetic nephropathy, and insulin sensitivity." (PMID 23922565, 2013). "When evaluating IGFBP1 DNA methylation levels in type 2 diabetes patients according to FHD, we found that newly diagnosed patients with FHD not only had higher fasting glucose and insulin levels but also increased IGFBP1 DNA methylation." (PMID 24246027, 2013). "Patients with diabetes mellitus type II (DM II) benefit from glibenclamide treatment, which inhibits KATP (Sur1-Kir6.2) channels in pancreatic β islet cells and leads to increased insulin release." (PMID 24275850, 2013). "Because insulin treatment increases the frequency and severity of hypoglycaemia, associations with accidents in these studies may not generalize to populations with type 2 diabetes who are not treated with insulin." (PMID 23121373, 2013). "Furthermore, if pharmacologically induced hypoglycaemia is more dangerous to patients with Type 2 diabetes than previously recognized, this would of course only be relevant to treatment with the potential of inducing hypoglycaemia, i.e. sulphonylureas, meglitinides and insulin." (PMID 23350893, 2013). "DM2, also called noninsulin-dependent diabetes mellitus (NIDDM), is characterized by insulin resistance with significant metabolic dysfunction including obesity, impaired insulin function and secretion, and increased endogenous glucose output." (PMID 23841103, 2013). "SIRT1 regulate insulin secretion in pancreatic β cells and SIRT3 is suppressed in pancreatic islets isolated from human type 2 diabetic patients." (PMID 24073959, 2013). "Although the wild type mouse strain varies in their ability to secrete insulin in response to HFD, 8 weeks-HFD-fed C57BL/6J mice are still quite a good model of type 2 diabetes." (PMID 23675258, 2012). "None of these women displayed any knowledge of a possible link between insulin use in GDM and subsequent development of type 2 diabetes." (PMID 22988897, 2012). "The depletion of iron stores via phlebotomy has been shown to improve insulin sensitivity in patients with NAFLD and type II diabetes." (PMID 23119080, 2012). "The relationship between insulin sensitivity, CFR and VO2peak was still present when removing the 8 patients with type 2 diabetes (r = 0.48, p = 0.006 and r = 0.49, p = 0.006 respectively)." (PMID 22889317, 2012). "Thiazolidinediones (TZDs) act through peroxisome proliferator activated receptor (PPAR) γ to increase insulin sensitivity in type 2 diabetes (T2DM), but deleterious effects of these ligands mean that selective modulators with improved clinical profiles are needed." (PMID 22649490, 2012). "Similar to type 2 diabetes, GDM is manifested by the inability of pancreatic β-cell insulin release to compensate for pregnancy-induced insulin resistance resulting in maternal hyperglycaemia and hyperinsulinaemia." (PMID 22675354, 2012). "Human IAPP, islet amyloid deposits of which are found in type 2 diabetes, aggregates in the ECM and induces apoptosis and defects in insulin secretion." (PMID 22460761, 2012).
type 2 diabetes (continued). "Sitagliptin is an oral medication indicated for type 2 diabetes mellitus (T2DM) and prevents inactivation of GLP-1 by selectively inhibiting DPP-4, thus increasing insulin secretion and decreasing glucagon concentration in a glucose-dependent manner." (PMID 23056044, 2012). "Impaired insulin-induced GLUT4 traffic and phosphorylation of TBC1D4 are restored by endurance exercise-training in skeletal muscle of type 2 diabetes patients." (PMID 22253718, 2012). "However, type 2 diabetes is a progressive disorder and, as a result, patients who may start with diet and lifestyle modifications will frequently progress to oral hypoglycaemic agents and/or insulin therapy to maintain their glucose control." (PMID 22613296, 2012). "Our data suggest that, in routine practice, people with type 2 diabetes and initially poor glycaemic control have a similar risk of major macrovascular events (MI, acute coronary syndrome, stroke or death) in the medium term regardless of what type of insulin is started." (PMID 23166795, 2012). "This association suggests that the functional significance of these SNPs in type 2 diabetes is relayed through the expression of IDE, which plays a central role in insulin metabolism." (PMID 22584726, 2012). "In patients with type 2 diabetes, DPP-4 inhibition leads to higher levels of active incretins, both during fasting and post meal, which in turn lead to higher insulin release, lower glucagon levels, and improved fasting and post meal glucose concentrations." (PMID 23554750, 2012). "Since PPARγ is also involved in glucose metabolism improving insulin sensitivity, selective ligands such as the thiazolidinediones (TZD) are used as insulin-sensitizing drugs in type 2 diabetes." (PMID 22991505, 2012). "The ‘incretin effect’ is significantly reduced in patients with type 2 diabetes mellitus (T2DM) and contributes to impaired insulin secretion and chronic hyperglycemia." (PMID 22761701, 2012). "The different therapies available for Type 2 diabetes (T2DM) include lifestyle modification of diet and exercise, oral medications and insulin." (PMID 22240113, 2012). "However, several lines of evidence has shown that insulin dramatically suppresses the production of SeP in the hepatocytes, suggesting that decreased insulin action in the liver may induces the elevation of circulating SeP in patients with type 2 diabetes." (PMID 22496878, 2012). "Fasting glucose, plasma insulin, and HOMA2-IR levels were higher, whereas plasma total cholesterol, LDL cholesterol, HDL cholesterol levels were lower in the patients with type 2 diabetes than in the control subjects." (PMID 22615949, 2012). "Type 2 diabetes mellitus (T2DM) is a chronic, debilitating disease characterized by insulin resistance, impaired insulin secretion, and hyperglycaemia." (PMID 21766562, 2011). "In another study, with type 2 diabetic patients, in which TLR expression in mononuclear cells was monitored in response to low-dose insulin infusion, a further relationship between TLR2 and TLR4, and insulin homeostasis was identified." (PMID 21356084, 2011). "It is interesting that one of the pathways affected by Ankrd2 silencing is the Insulin signaling pathway especially since DARP, a MARP family member, is up regulated in type 2 diabetes and thought to have a role in glucose uptake in muscle." (PMID 22016770, 2011). "As TRPM5 appears to be involved in glucose-dependent insulin secretion, TRPM5 dysfunction has been suggested to be a factor in the etiology of some forms of type 2 diabetes." (PMID 21420431, 2011). "The effect is to reduce fasting and post-prandial glucose and insulin levels, triglycerides and atherogenic LDL-cholesterol, notably in obese animals and subjects with type 2 diabetes." (PMID 21144857, 2011).
type 2 diabetes (continued). "These were a cross-over study of biphasic insulin aspart 30 (BIAsp30) versus biphasic human insulin 30 (BHI 30) in 13 type 2 diabetic patients and a randomized controlled trial of BIAsp 30 versus BHI 30 in 294 patients with type 1 and type 2 diabetes." (PMID 20438630, 2010). "Insulin and IGF2 (11p15.5) are candidate genes for complex traits, including type I diabetes mellitus (T1DM), type II diabetes mellitus (T2DM) and obesity with onset especially in childhood and middle-age." (PMID 21637566, 2010). "Insulin, the TZDs, MET, and the GLP-1 receptor agonists show fairly robust effects on lipid levels in patients with type 2 diabetes." (PMID 20804556, 2010). "Inevitably, intensive insulin therapy is to be considered for reaching HbA1C targets, as supported by UKPDS, which showed that >60% of type 2 diabetic patients will need insulin within 5 years of diagnosis." (PMID 20589066, 2010). "Recent studies comparing the long-acting insulin analogue glargine (GLA) vs. NPH insulin in combination with metformin revealed the advantages of insulin GLA, owing to its flat and long-lasting pharmacodynamic profile in patients with type 2 diabetes." (PMID 20415692, 2010). "In a number of clinical trials, patients with type 2 diabetes exhibited comparable HbA1c reductions and rates of achieving target HbA1c goals (≤ 7.0%) when administered insulin glargine or NPH insulin." (PMID 20618882, 2010). "The goal of the recent study was to investigate the effect of basal insulin treatment, by adding insulin GLA or NPH insulin to metformin, on postprandial β-cell function in patients with type 2 diabetes using a combination of metformin and sulfonylurea." (PMID 20415692, 2010). "It is interesting that type 2 diabetes genes (e.g., KCNQ1 and SLC30A8) showed limited impacts on fasting glucose in the normoglycemic populations, although they also impaired insulin secretion." (PMID 20668700, 2010). "Impaired insulin action is considered the first stage of type 2 diabetes mellitus (T2DM)." (PMID 20508742, 2010). "In light of their pivotal role in insulin signalling, IRS proteins have been examined as candidate genes for type 2 diabetes and other human metabolic disorders." (PMID 20604929, 2010). "Our observation of high CD26/DPPIV expression, significant down expression of genes in the insulin signaling pathway and impaired fasting glucose state (IFG) implied an evolving type 2 diabetes condition among the HIV resistant commercial sex workers." (PMID 21108831, 2010). "It has been shown that losing ≥ 7% of body weight appear to improve insulin sensitivity and glycemic control in both individuals with IGT and type 2 diabetes." (PMID 19166627, 2009). "In healthy patients and those with type 2 diabetes, exogenous glucagon-like peptide-1 (GLP-1) decreases blood glucose by suppressing glucagon, stimulating insulin and slowing gastric emptying." (PMID 19439067, 2009). "In conclusion, 8 weeks of rosiglitazone treatment (2 × 4 mg/d) resulted in improved insulin sensitivity and lipid profile and reduced concentrations of plasma inflammatory markers (MCP1 and hsCRP) in type 2 diabetic patients." (PMID 19243600, 2009). "GLP-1 mimetics and inhibitors of GLP-1 degradation are already licensed for the treatment of type 2 diabetes, exploiting the important role of GLP-1 in the stimulation and maintenance of insulin release from pancreatic β cells and in the control of appetite." (PMID 19041768, 2008). "The palmitate-induced NO generation and associated suppression of glucose-stimulated insulin release is counteracted by ROZ at the GPR40 receptor, and thus, ROZ and other thiazolidinedione drugs might be beneficial for β-cell function in hyperlipidemic type 2 diabetes.." (PMID 18478115, 2008).
type 2 diabetes (continued). "The ability of an insulin insensitive individual's beta cells to compensate for IR by producing extra quantities of insulin in response to a glucose load may decrease with age and elevated glucose is a relatively late feature in the natural history of progression to type II diabetes." (PMID 17300718, 2007). "In this study, although plasma glucose levels remained unchanged during the experiments, short-term treatment of telmisartan (2 weeks) decreased plasma insulin, TG, and NEFA levels in KK-Ay mice, an obese type 2 diabetic animal model." (PMID 23675001, 2006). "Results from both models of type 2 diabetes demonstrate some abnormalities in pHi-regulation, and consistently favorable effects of DMA/amiloride on both direct insulin secretion and TDP in isolated islets." (PMID 16336655, 2005). "We conducted a prospective, nonrandomized study of hospitalized adults with type 2 diabetes, HbA1c > 8%, and requiring ≥10 units of basal insulin daily." (PMID 41376653, 2026). "At age 14, she developed type 2 diabetes with preserved insulin secretion and negative autoimmune markers." (PMID 41631087, 2026). "Glucose-related outcomes remain stable in healthy adults, although reductions in total glucose exposure have been reported in type 2 diabetes (T2D) without concurrent changes in insulin." (PMID 41515267, 2026). "Interestingly, sub-chronic indole treatment improved insulin sensitivity in both healthy mice and diabetic mice models, with the most pronounced effect being observed in the TALLYHO/JnG model of type 2 diabetes." (PMID 41776124, 2026). "High C-peptide values above 0.6 nmol/l (termed C-peptide HI) typically seen in type 2 diabetes and indicative of a lack of insulin requirement were detected in 36.5% (n=97)." (PMID 41175199, 2026). "It would also be beneficial to explore whether the prescribing of GLM other than metformin and insulin varies by SMI status, particularly in response to recent changes to clinical guidance on GLM prescribing for people with type 2 diabetes." (PMID 41235789, 2026). "The addition of insulin sensitizers (metformin and pioglitazone) or sitagliptin to short‐term intensive insulin therapy (SIIT) facilitated SIIT implementation and enhanced short‐term glycemic control in patients with newly diagnosed type 2 diabetes." (PMID 41521023, 2026). "Type 2 diabetes (T2D) develops when beta cells within pancreatic islets no longer secrete sufficient insulin to lower circulating blood glucose levels, usually in the presence of insulin resistance." (PMID 39811653, 2025). "Human trials further support its potential, revealing improvements in insulin sensitivity and metabolic health and thus suggest that EGCG could be a valuable tool in the fight against type 2 diabetes." (PMID 41155632, 2025). "Our results suggest that, in individuals without obesity or type 2 diabetes, postprandial insulin plays a key role in inhibiting ZAG’s lipolytic actions, thereby facilitating adipogenesis." (PMID 40564902, 2025). "In this study, exposure to type 2 diabetes, but not gestational diabetes, impacted cord blood levels of glucose, insulin and leptin and birthweight." (PMID 40045330, 2025). "Long‐acting (basal) insulin remains an essential component of therapeutic strategies in patients with type 2 diabetes who do not achieve adequate glycaemic control with oral or non‐insulin injectable agents." (PMID 41152194, 2025). "In patients with type 2 diabetes, IR does not worsen with the onset of hyperglycemia; however, insulin secretion decreases over time." (PMID 40674363, 2025). "As demonstrated by studies such as TODAY (The Treatment Options for Type 2 Diabetes in Adolescents and Youth) and RISE (Restoring Insulin Secretion), there is a relatively rapid deterioration of beta-cell function in adolescents compared to the slower decline described in adults with T2DM." (PMID 39147370, 2025).
type 2 diabetes (continued). "These monoamines activate the extracellular signal-regulated kinase (ERK) pathway, which drives cellular stress responses, while inhibiting AKT (protein kinase B), a key regulator of insulin-stimulated glucose uptake, thereby resulting in insulin resistance in IBS and type 2 diabetes patients." (PMID 41036868, 2025). "Compared with other studies of CGM use among people with type 2 diabetes not on insulin therapy, the A1c change described in this study was lower (−0.45% crude or −0.28% after adjusting for covariates) compared to −3.0% in Grace and –1.6% in Wright." (PMID 40851538, 2025). "In conclusion, the type 2 diabetes condition blunts the metabolic transcriptional response to HIIT in the type IIA myonuclei without affecting the improvement in insulin sensitivity." (PMID 40413649, 2025). "It has also been shown that the administration of Z. officinale powder to participants with type-2 diabetes who have NAFLD increased HDL and decreased BMI, waist and hip circumferences, amounts of liver transaminase, serum insulin, and HOMA-IR compared to the baseline." (PMID 40343290, 2025). "The effects of exercise on insulin and glucagon were consistent across participants with and without type 2 diabetes." (PMID 40580209, 2025). "In contrast to CFRD, the pathophysiology of Type 2 Diabetes (T2D) is driven by insulin resistance, not insulin secretion." (PMID 40806116, 2025). "Some key aspects of medical management for both type 1 and type 2 diabetes are as follows: i) For type 1 diabetes: Insulin treatment is essential, and individuals not receiving it can experience severe health complications." (PMID 39563945, 2025). "In Type 2 diabetes (T2D), insulin is still produced, but the lack of proper cellular responses to insulin results in high blood sugar." (PMID 40565059, 2025). "The CIMT trial in type 2 diabetes patients on insulin mirrored these findings, with no significant change in CIMT between the Metformin and placebo groups." (PMID 41267359, 2025). "In type 2 diabetes, the body either becomes resistant to insulin or does not produce enough insulin." (PMID 40416402, 2025). "Empagliflozin (EMPA) is a sodium‐glucose cotransporter 2 (SGLT2) inhibitor used as an oral medication for treating and managing type 2 diabetes mellitus (T2DM) by improving glycaemic control, reducing glucotoxicity, enhancing glucose metabolism, and decreasing insulin resistance." (PMID 41376177, 2025). "Although KPD patients are initially insulin-dependent, after a few months of insulin treatment, roughly 70% undergo near-normoglycemia remission and can maintain blood glucose without insulin, as in early type 2 diabetes or prediabetes." (PMID 38895272, 2025). "Type 2 diabetes mellitus (T2DM) is a renowned overgrowing endocrine metabolic disease, and occurs as a result of insulin resistance (IR) and inadequate insulin production, resulting in hyperglycemia, presenting a substantial burden on global healthcare systems." (PMID 40416523, 2025). "Furthermore, chronic inflammation in metabolic diseases such as type 2 diabetes mellitus (T2DM) and obesity is known to impair insulin sensitivity and promote systemic inflammation, leading to cardiovascular complications." (PMID 40390731, 2025). "It has been observed that taking P. oleracea seeds reduced body weight, BMI, insulin, fasting and postprandial blood glucose, serum levels of LDL, TC, TG, GGT, AST, ALT, and direct and total bilirubin in obese individuals with type-2 diabetes in comparison to the metformin group." (PMID 40343290, 2025). "Higher insulin, C-peptide, and triglyceride levels, as well as lower HDL-C and ApoA1 levels with low-grade inflammation, accompany the obesity and type 2 diabetes, while abnormal HbA1c levels were measured accordingly only in patients with type 2 diabetes." (PMID 41226333, 2025).